CD36 (CD36 molecule (CD36 blood group))
Diseases named in the same sentence as CD36 in open-access papers (continued):
Sharing a sentence is not in itself a finding about the gene and the disease.
Insulin resistance (continued). "Deficiency of CD36 in LECs highlights a new mechanism for the etiology of visceral obesity and insulin resistance, two phenotypes linked to the metabolic syndrome, which increases risk of cardiovascular disease and T2D, pathologies that associate with CD36 genetic variants." (PMID 34099721, 2021). "Here, the authors found that lymphatic vessel integrity and lipid transport are influenced by CD36 expression, and lymphatic endothelial cell CD36 deficiency causes visceral obesity and insulin resistance, which are risk factors for metabolic syndrome and diabetes." (PMID 34099721, 2021). "However, researchers rather indicate the association of CD36 with pathogenesis of hepatosteatosis and liver insulin resistance." (PMID 32796572, 2020). "In both animal and human studies, increased CD36 expression in metabolically active tissue has been implicated in regulation of fatty acid metabolism and enhancement of fatty acid internalization and lipid accumulation, thus leading to insulin resistance." (PMID 31429730, 2019). "Hyperlipidemia and insulin resistance have been reported in Cd36-deficient mice and humans." (PMID 30201044, 2018). "Deficiency of Cd36 in SHR rats, shown to be associated with insulin resistance, could be corrected by exogenously expressed Cd36." (PMID 30201044, 2018). "Transgenic mice overexpressing CD36 have reduced blood lipids and deficiency of CD36 could lead to insulin resistance." (PMID 27483138, 2016). "Hepatic expression of CD36 is abnormally increased in non-alcoholic fatty liver disease, and a previous study indicated that hepatic CD36 upregulation was significantly associated with insulin resistance, hyperinsulinemia and increased steatosis in patients with NAFLD." (PMID 25310357, 2014). "The relationship between CD36 deficiency and insulin resistance remains controversial." (PMID 24016701, 2013). "CD36 deficient humans were reported to have insulin resistance." (PMID 22662181, 2012). "An up-regulation of CD36 in liver cells has also been associated with insulin resistance." (PMID 22969728, 2012). "Moreover, another large-scale genome-wide linkage scan among 8664 participants from multiple ethnicities showed that 7q36, a site for CD36, was associated with fasting glucose and insulin resistance." (PMID 23249574, 2012). "In contrast, animals over expressing CD36 in muscle exhibited decreased plasma concentrations of triglycerides and increased plasma insulin and glucose concentrations and CD36 deficiency induced insulin resistance in the liver of these animals." (PMID 22662181, 2012). "Insulin resistance in the intestine has been associated with increased apolipoproteins, chylomicrons, de novo lipogenesis, and increased fatty acid and cholesterol uptake via CD36 and SCARB1." (PMID 22073239, 2011). "Paradoxically, it has also been shown that human CD36 deficiency co-exists with insulin resistance." (PMID 19924273, 2008). "Moreover, considering the significance of CD36 in prediabetes, the redistribution of CD36 in cardiomyocytes from intracellular compartments to the sarcolemma is one of the earliest changes in insulin resistance, which has a significant positive association with CAS." (PMID 41011253, 2025). "PPARγ regulates CD36 expression by virtue of a PPARγ responsive element in the proximal region of CD36 promoter, and CD36 deficiency reduces fatty acid uptake and may lead to insulin resistance, which indicates CD36 is metabolically protective in adipose and muscle tissues." (PMID 34440852, 2021). "Since a patient with CD36 deficiency was found in Japan in the 1990s, numerous studies have reported that the patients with CD36 deficiency had the typical metabolic features of MetS, such as dyslipidemia, including postprandial hypertriglyceridemia, insulin resistance, and hypertension." (PMID 33995128, 2021).
Insulin resistance (continued). "CD36 is, quantitatively, the most important scavenger receptor for uptake of oxidized lipoproteins by hepatocytes, and previous studies have shown that its upregulation is associated with insulin resistance, hyper-insulinemia, and increased steatosis in patients with NASH." (PMID 31394746, 2019). "CD36 expression or function are involved in angiogenesis, macrophage and platelet activation, lipid metabolism, and inflammation, which influences susceptibility to certain metabolic diseases, such as obesity, insulin resistance, impaired glucose tolerance, and fatty liver disease." (PMID 31109109, 2019). "Vitamin E ameliorates insulin resistance by down-regulating CD36 and up-regulating PPAR-γ-dependent adiponectin and improves oxidative stress by reducing ox-LDL and MDA production." (PMID 40725208, 2025). "Preferential localisation of CD36 to the sarcolemma is one of the initiating cellular responses in the development of muscle insulin resistance and in the type 2 diabetic heart." (PMID 40357580, 2025). "and decreased abundance of Treponema, F. succinogenes, Christensenellaceae and F16, promoted the absorption of excess PA by regulating the expression of IL-17A and Cd36, leading to the LCFAs accumulation and insulin resistance." (PMID 40878918, 2025). "Recent investigations indicate a notable correlation between the increased expression of hepatic CD36 and insulin resistance, hyperinsulinemia, and heightened steatosis in NASH." (PMID 40002783, 2025). "In early-onset cardiac insulin resistance and chronic lipid overload, CD36 and GLUT4 behave in a bio-dysregulated manner." (PMID 40565598, 2025). "CD36 promotes the accumulation of lipids and activation of immune cells, such as macrophages, which contributes to insulin resistance and β-cell dysfunction." (PMID 41465460, 2025). "(I) Specific gut microbiota structure promoted the absorption of excess PA by regulating the expression of IL-17A and Cd36, leading to the LCFAs accumulation and insulin resistance." (PMID 40878918, 2025). "CD36 dynamics are further modulated through palmitoylation-regulated endocytosis, which is disrupted in insulin resistance, impairing CD36 internalization and enhancing FA uptake." (PMID 41002965, 2025). "Knockdown of hepatic Cd36 prevents systemic inflammation and improves insulin resistance of HFD‐fed mice." (PMID 38506086, 2024). "We also observed that female Adra1bLKO mice fed an obesogenic diet had increased expression of Cd36, a fatty acid transporter whose expression is related to insulin resistance, inflammation, and steatosis." (PMID 39259165, 2024). "Insulin resistance induces CD36 upregulation, promoting the accumulation of inflammation and lipids, worsening myocardial metabolic disorders." (PMID 39396974, 2024). "Resveratrol is a stilbenoid attenuating high-fat-diet-induced insulin resistance by influencing skeletal muscle lipid transport and subsarcolemmal mitochondrial β oxidation and inhibiting the expression of CD36 in high-fat-diet mice." (PMID 39125700, 2024). "In line, disruption of hepatic CD36 protected against NAFLD-associated systemic inflammation and insulin resistance, by reducing hepatic FFA uptake and ectopic lipid deposition in HFD-fed mice." (PMID 38024380, 2023). "CD36 is mainly involved in insulin resistance, AMPK signaling pathway, Adipocytokine signaling pathway and fat digestion and absorption." (PMID 37248406, 2023). "Although palmitoylation is necessary for normal protein functioning, inappropriate palmitoylation resulting from lipid overload has been shown to worsen insulin resistance by disrupting the functionality of proteins like CD36 and GLUT4." (PMID 38136203, 2023). "Obviously, it needed further validation to clarify the detailed role of CD36 in DKK1-induced insulin resistance." (PMID 36410795, 2023).
Insulin resistance (continued). "While findings have occasionally varied, soluble CD36 has been proposed as a potential marker for insulin resistance in diabetes and as a prognostic indicator for DKD." (PMID 38136203, 2023). "Among these, CD36-dependent mechanisms are important in the development of insulin resistance and, subsequently, in the pathogenesis of DCM53." (PMID 37009790, 2023). "As a scavenger receptor for free fatty acids, CD36 is widely expressed on β cells and α cells in pancreatic islets and contributes to insulin resistance and diabetes." (PMID 35343389, 2022). "This study found that the increased hepatic BCL6 expression sufficiently inhibits CD36 gene expression and subsequent hepatic lipid accumulation, while also exerting a positive effect on insulin resistance in HFD-fed mice." (PMID 35436984, 2022). "CD36 also plays a significant role in lipid and glucose metabolism, and can promote insulin resistance and hyperinsulinemia." (PMID 33854480, 2021). "CD36 is a multi-functional scavenger receptor with multiple ligands, which plays important roles in developing hyperlipidemia, insulin resistance, and metabolic syndrome." (PMID 33995128, 2021). "Adipose tissue cluster of differentiation 36 (CD36) and adaptor protein 2 (AP2) are associated to fatty acid accumulation and play a role in inflammation and insulin resistance." (PMID 34948369, 2021). "An in vivo study showed that insulin resistance and inflammatory factor release were reduced in CD36-knockout mice, indicating that CD36 plays a vital role in humans." (PMID 34307504, 2021). "The CD36, GLUL, MYH11, CD163, and COL4A2 genes were closely associated with weight loss, while the ACACB gene was closely related to insulin resistance." (PMID 34085602, 2021). "Increased CD36-mediated fatty acid uptake and lipid accumulation precede the development of insulin resistance." (PMID 34265467, 2021). "Modifications of lipid metabolism upon chronic FA oversupply interceded by CD36 lead to the accumulation of specific lipid species that are especially critical for the development of insulin resistance." (PMID 34360006, 2021). "The role of CD36 in the pathomechanism of insulin resistance in particular tissues has been demonstrated by many researchers and requires a separate discussion." (PMID 32796572, 2020). "CD36 is important in prediabetes when it participates in the development of insulin resistance in adipose tissue, the liver, skeletal muscles, and the heart." (PMID 32796572, 2020). "All the experimental results indicate that abnormal distribution of CD36 on cell membrane is a precondition that mediates excess fatty acid uptake prior to insulin resistance." (PMID 31938068, 2020). "We suppose that this is the result of internalization of adipocytic CD36 in response to excess FA generated during adipose lipolysis typical for insulin resistance." (PMID 32796572, 2020). "The alterations in lipid metabolism upon FA oversupply mediated by CD36 are particularly important for the development of insulin resistance." (PMID 32796572, 2020). "It is likely that sCD36 level reflects early changes in surface CD36 expression in some tissues as a result of developing insulin resistance." (PMID 32796572, 2020). "CD36 accumulation at the plasma membrane typically represents the first step leading to the onset of lipid-induced insulin resistance partly via CER or DAG (see Section 2.2)." (PMID 33322406, 2020). "T2DM related to factors such as insulin resistance, high oxLDL, systemic low-grade inflammation, or hepatosteatosis, stimulates CD36 expression in monocytes and macrophages localized in adipose tissue, the liver, and arteries leading to elevated plasma sCD36." (PMID 32796572, 2020). "The in vivo experimental data indicated that CD36 had translocated to sarcolemma before the onset of insulin resistance in HFD fed mice." (PMID 31938068, 2020).
Insulin resistance (continued). "We previously identified v-ATPase as a mediator of lipid-induced CD36 relocation to the sarcolemma and the resulting lipid accumulation and development of cardiac insulin resistance." (PMID 30673728, 2019). "In monocytes and macrophages, CD36 is up-regulated by hyperglycaemia, insulin resistance, and oxLDL." (PMID 31109109, 2019). "Genetic manipulations of Cd36 in rodent/rat models have indicated an important role of this molecule in insulin resistance, glucose intolerance, dyslipidemia, hypertension, and coronary heart disease." (PMID 31748580, 2019). "In contrast abnormal myocardial fatty acid uptake via redistribution of CD36 from intracellular stores to the plasma membrane was found in early stages of insulin resistance contributing to cardiac lipotoxicity." (PMID 31547508, 2019). "Previous studies demonstrated that CD36 is involved in various diseases, such as insulin resistance, atherosclerosis, and non-alcoholic fatty liver disease (NAFLD)." (PMID 30016988, 2018). "On the other hand, it has been demonstrated that soluble CD36 in plasma is an insulin-resistance marker." (PMID 28729885, 2017). "On the other hand, we have recently demonstrated that mangiferin, a xanthone glucoside, also mitigates fructose-induced insulin resistance via modulation of CD36 redistribution in the skeletal muscle of Wistar-Kyoto rats." (PMID 27405506, 2016). "Conversely, Cd36 was borderline elevated in mice that had increased insulin resistance (p = 0.055) and in those that had met criteria for NAFLD (p = 0.055)." (PMID 27124954, 2016). "CD36 is involved in a number of metabolic pathways, and contributes to development of insulin resistance and the metabolic syndrome." (PMID 27405506, 2016). "In summary, we show that increased intake of sucrose in CBA mice results in rapid development of hyperinsulinemia, hepatosteatosis, and insulin resistance and that insulin enhances hepatic expression of the FA transporter Cd36 in a Pparγ-dependent manner." (PMID 26085100, 2015). "HP/HI induced insulin resistance and lipid storage was accompanied by increased Cd36, Acot1, and Ucp3 mRNA levels." (PMID 26649034, 2015). "Here, we present in vivo and ex vivo data providing evidence that increased circulating levels of insulin trigger fatty liver development and insulin resistance by stimulating hepatic expression of the FA transporter Cd36 in a Pparγ-dependent manner." (PMID 26085100, 2015). "Here, we have explored the effect of hyperinsulinemia on hepatic Cd36 expression, development of hepatosteatosis, insulin resistance, and dysglycemia." (PMID 26085100, 2015). "Higher levels of monocyte CD36 and plasma CD36(sCD36) are seen to cluster with insulin resistance and diabetes." (PMID 24069322, 2013). "Increased levels of CD36 in monocytes among diabetic patients are highly correlated with insulin resistance." (PMID 24282409, 2013). "The transgenic expression of CD36 in the hypertensive rat model showed the decreased metabolic syndrome and insulin resistance burden." (PMID 23249574, 2012). "Genetic variation in fatty acid translocase CD36 has been previously linked with dyslipidemia and insulin resistance both in experimental models and in human subjects." (PMID 20398376, 2010). "Dexamethasone is known to induce whole body insulin resistance and affect lipid metabolism after both short and long-term administration while CD36 is one of its target genes." (PMID 20398376, 2010). "The class B scavenger receptor CD36 and the class A scavenger receptor SR-A are considered two of the most important for foam cell formation and are increased in the presence of insulin resistance." (PMID 17551591, 2007). "In the liver, CD36 drives lipotoxic uptake, insulin resistance and steatosis." (PMID 40725208, 2025). "CD36 is involved in several processes including oro-sensory perception of dietary lipids, inflammatory responses, angiogenesis, metabolism, and regulation of the metabolic pathways of insulin-resistance." (PMID 37960309, 2023).
Insulin resistance (continued). "By contrast, higher insulin levels could enhance liver Cd36 expression and induce steatosis and hepatic insulin resistance." (PMID 37852177, 2023). "In addition, several energy metabolic processes, such as the PI3K-Akt pathway (EPHA2, FLT4, ITGA5, and LPAR6), cholesterol metabolism (APOE and CD36), and insulin resistance (FOLR1, CALM14, and PPP1R3A), were enriched in ApoE4 mice." (PMID 36720919, 2023). "The results showed that CD36 deletion protected myotubes from insulin resistance in the presence of PA overload, probably because CD36 deletion reduced the uptake of excess LCFAs and alleviated lipid overaccumulation, thus improving the insulin signaling pathway." (PMID 36979708, 2023). "In addition, upregulation of hepatic CD36 is closely related to insulin resistance and hepatic fatty content in patients with NASH." (PMID 35436984, 2022). "Currently, the regulatory effect of CD36 on insulin resistance is still controversial." (PMID 36213291, 2022). "CD36 is involved in the uptake of fatty acids, and several studies have indicated that there are relationships between elevated CD36 expression in different tissues and insulin resistance." (PMID 35982478, 2022). "LBW combined with high-fat diets may increase insulin resistance and diabetes through regulating the CD36-related Fabp4-PPARγ and AMPK/ACC signaling pathways." (PMID 34983495, 2022). "This may suggest that CD36-dependent EC inflammation contributes to systemic inflammatory pathways leading to insulin resistance." (PMID 34888367, 2021). "However, the improvement of insulin resistance by the 4∗KLR treatment using CD36 internalization in muscle comes at a cost." (PMID 34265467, 2021). "In hyperlipidemia patients, CD36 expression was abnormal, and increased CD36 expression could result in endoplasmic reticulum (ER) stress, macrophage apoptosis, insulin resistance, and CVD." (PMID 34307504, 2021). "Understanding this complex situation and the therapeutic agents that modulate the CD36 function could have a considerable impact on the treatment of metabolic diseases such as insulin resistance and diabetes." (PMID 34360006, 2021). "It is unclear, however, whether the participation of CD36 in the mechanism of insulin resistance in adipose tissue relies more on modulating lipid storage or directly to lipolysis." (PMID 32796572, 2020). "Second, we speculate how protein hyper-palmitoylations (including that of CD36), as they occur during lipid oversupply, may lead to insulin resistance." (PMID 33322406, 2020). "Therefore, the role of CD36 in long-chain FA uptake into cardiac and skeletal myocytes is particularly important in insulin resistance pathogenesis." (PMID 32796572, 2020). "It is worth mentioning here that dietary FAs are capable of modulating the deleterious effects of insulin resistance by alterations to the functionalities of membrane proteins involved in insulin activity—among others, CD36—and their effects on the metabolism of glucose and FAs." (PMID 32796572, 2020). "This provides evidence for the importance of predisposition for T2DM in obese individuals that may mediate both insulin resistance and impaired insulin secretion dependent on CD36." (PMID 32796572, 2020). "The relocation of CD36 precedes the onset of muscle insulin resistance with GLUT-4 retained intracellularly and decreases the incorporation of glucose into glycogen, the development of which is a long-term process, which requires the participation of many mechanisms." (PMID 32796572, 2020). "However, it was uncertain how CD36 translocates to plasma membrane for mediation of FA uptake upon FA being the dominant energy source and prior to insulin resistance." (PMID 31938068, 2020).